EPHA5 (EPH receptor A5)
Diseases named in the same sentence as EPHA5 in open-access papers (continued):
Sharing a sentence is not in itself a finding about the gene and the disease.
tumor (continued). "It is possible that EphA5 contributes to tumor cell proliferation under certain conditions but also engages in protective or compensatory pathways that enhance long-term outcomes." (PMID 40806980, 2025). "In stage I tumors, the EphA5 expression level was positively correlated with the Ki-67 expression level and inversely with the tumor grade and pAMPK expression level." (PMID 40806980, 2025). "Recent evidence suggests that decreased EphA5 expression is associated with nodal metastasis, advanced TNM stages and unfavorable prognosis in CRC, implicating EphA5 as a potential tumor suppressor." (PMID 38651144, 2024). "Given its potential role as a tumor suppressor, further studies are warranted to fully elucidate the significance of EphA5 in CRC progression and its implications for clinical management." (PMID 38651144, 2024). "Accordingly, Almog and colleagues, reported that angiomotin and tropomyosin were upregulated in dormant tumour cells, while EphA5 was increased in the blood of mice with dormant tumour cells." (PMID 35563661, 2022). "This study suggested that EphA2, EphA3, EphA4, and EphA5 can act as tumor-inhibiting factors as well as biomarkers for the prognosis of BC." (PMID 34221956, 2021). "EPHA5, in consistency with its tumor suppressive properties on other solid tumors, exhibits a protective role in ovarian cancer, with its negative or weak expression linked to poor clinical outcomes." (PMID 34445116, 2021). "First, we established the relationship between EPHA5 and antitumor immunity based only on data from tumor specimens." (PMID 33288738, 2020). "Two important targets of miR-580 and miR-190 are the EphA5 and Angiomotin genes, both are expressed in dormant tumors, are inversely related to tumor stage and down regulated during the angiogenic switch." (PMID 30180883, 2018). "Several studies have provided evidence that EphA5 is frequently downregulated in various cancer cell lines and tumor tissues via aberrant hypermethylation of its promoter." (PMID 27057165, 2016). "Numerous reports have demonstrated that, similarly to the other members of the Eph family, EphA5 not only is involved in a variety of developmental processes, but also plays important roles in carcinogenesis and the tumor progression of many cancers." (PMID 25609195, 2015). "Given that EphA5 is expressed in the developing and adult central nervous system, we also quantified 11C12 in the brain of tumor-bearing rats and found it to be at background levels." (PMID 25623065, 2015). "EphA4 expression was significantly associated with the presence of inflammation (p = 0.025) and EphA5 expression with tumor proliferative capacity (p = 0.023)." (PMID 24495444, 2014). "These functional investigations will be critical to determine whether EphA5 acts as a true driver of prognosis or merely reflects broader tumor microenvironmental dynamics." (PMID 40806980, 2025). "Given the established role of EphA5 in tumor progression and immune modulation across various malignancies, including lung, colorectal, and ovarian cancers, it may serve as a context-dependent biomarker of patient outcomes." (PMID 40806980, 2025). "Concordantly, and despite our efforts to characterize the expression of EphA5 in solid human tumors and PDX models, a clear correlation between EphA5 expression, whether membranous or cytoplasmic, and tumor response has yet to be established." (PMID 40662373, 2025). "In summary, while EphA2 promotes cancer progression in ESCC, EphA7, EphA3, and EphA5 act as tumor suppressors, suggesting that members of the Eph family may have opposing effects depending on the tumor context." (PMID 39839790, 2024). "Additionally, EPHA5 overexpression was correlated with tumor proliferative capacity and longer OS and EPHA7 overexpression correlated with tumor proliferative capacity and older age, presence of fibrosis, as well as with smaller tumor size." (PMID 34445116, 2021).
tumor (continued). "In previous studies, the methylation of EphA5 was associated with later tumor stages and progesterone receptor-negative status in BC." (PMID 34221956, 2021). "As EPHA5 is known to be significantly upregulated in SCCOHT as well, Ephrin signaling might be one of the tumor-promoting pathways in tumors driven by SMARCA4 deficiency." (PMID 33331994, 2021). "This difference may explain the more abundant infiltration of TILs in the EPHA5-Mut TME than in the EPHA5-WT TME, as these mutated neoantigens can be recognized by TILs and induce tumor-specific immune responses." (PMID 33288738, 2020). "Thus, for the first time, we identified the link between EPHA5 and the tumor immune microenvironment in LUAD." (PMID 33288738, 2020). "Previous reports suggested that EphA5 is involved in regulation of tumor dormancy." (PMID 27057165, 2016). "Finally, we conducted a subgroup analysis to compare the median expression levels and interquartile ranges (IQRs) of various tumor-related biomarkers between low and high EphA5 expression groups across different FIGO stages (I–III), along with the corresponding p-values." (PMID 40806980, 2025). "Similarly, SMARCA4-deficient MRTs, such as AT/RTs, have been noted for exhibiting high expression levels of EPHA5, indicating that the Ephrin signaling pathway may be tumor-promoting in SMARCA4-driven malignancies." (PMID 38893160, 2024). "In summary, most Eph receptors (EphA1, EphA2, EphA3, EphA4, EphA5, and EphA7) function as promoters of GC progression, influencing metastasis, tumor invasion, angiogenesis, and drug resistance, while EphA1 has a more complex role depending on tumor differentiation." (PMID 39839790, 2024). "Based on our results, we concluded that EphA2, EphA3, EphA4, and EphA5 were down-regulated in BCs, and high expression levels of these genes indicated better RFS, suggesting that EphA2, EphA3, EphA4, and EphA5 act as tumor suppressors in BC and could be new biomarkers for its prognosis." (PMID 34221956, 2021). "Moreover, detection of circulating EphA5 protein levels correlated with tumor dormancy phase." (PMID 22952847, 2012). "Collectively, these findings point to a multifaceted role of EphA5 in modulating tumor behavior across cancers, possibly through the intersection of proliferative and metabolic pathways, and suggest that its prognostic impact may vary according to tumor subtype and microenvironmental context." (PMID 40806980, 2025). "IHC staining determined that EphA5 expression in this TNBC PDX model was moderate and heterogenous, with most tumor cells displaying cytoplasmic staining, though some tumor cells displayed a clear membranous staining pattern." (PMID 40662373, 2025). "It was thus possible to identify genes (CNTN1, FAT3, EPHA3, EPHA5, NLGN1, etc.)that contribute to PC2 and are differentially expressed in radial glial cells between normal and tumor samples." (PMID 38609519, 2024). "We have previously shown that EGFR and MMP1 act as key players in PM motility and EMT (epithelial to mesenchymal transition)‐like changes, and EPHA5 and PARK2 have been described to both drive and inhibit tumor cell migration." (PMID 36550787, 2024). "In addition, angiomotin and tropomyosin (the binding proteins of angiostatin and endostatin, respectively) may mediate anti-angiogenic activities in dormant tumour cells, while Eph receptor 5 (EphA5), a receptor tyrosine kinase involved in angiogenesis, may be linked to dormancy." (PMID 35563661, 2022). "Tumor volume was strongly correlated with the CN amplifications of subclone 1–ERBB4, LRP1B, PTPRD, and EPHA5 CN all exhibited r ∈ [0.76,0.79] and p-value ∈ [4.8e-4, 9.4e-4]." (PMID 30560892, 2018). "Additionally, a low tumor grade and early FIGO stage seemed inversely related to the EphA5 expression level, although only the relationship with a FIGO stage III was significant (aOR: 0.06, p = 0.046)." (PMID 40806980, 2025).
tumor (continued). "Notably, in follicular thyroid carcinoma, EphA5 reportedly promotes tumor cell proliferation and suppresses apoptosis via activation of the STAT3 signaling pathway, implicating it in tumor progression and a poor prognosis." (PMID 40806980, 2025). "Additionally, a low tumor grade might have been inversely associated with the EphA5 expression level (aOR: 0.06; 95% CI: 0.00–1.05; and p = 0.054), and a FIGO stage III classification was independently associated with a lower EphA5 expression level (aOR: 0.06; 95% CI: 0.00–0.95; p = 0.046)." (PMID 40806980, 2025). "In addition, EphA5 and its coactivation with ALK and FGFR2 also represent potential targets for biological therapy and treatment of this type of tumor." (PMID 39839790, 2024). "In addition, a slightly increased expression (more than 2-fold) of EPHA5 and IGFBP5 was detectable at the edge of the tumor compared with the center." (PMID 32872409, 2020). "With regards to the dormancy phenomenon and the slightly increased expression of the dormancy markers EPHA5 and IGFBP5 at the edge of the tumor observed in our study, the only connection published to date is an induction of MCT4 and dormancy markers by hypoxia." (PMID 32872409, 2020). "Thus, ephrin-A5 could have been investigated as a potential tumor-suppressing ligand through the interaction with its tumor promoting receptors such as EPHA2, EPHA3, EPHA4, EPHA5, EPHA7, EPHA8, and EPHB2 in sarcomas." (PMID 35563562, 2022). "Given the known tumor-suppressive functions of AMPK through the inhibition of mTOR signaling and induction of energy stress responses, the negative correlation between EphA5 and pAMPK suggests that EphA5 expression may be attenuated in metabolically restrained tumor environments." (PMID 40806980, 2025).
cancer (25 papers, 2013 to 2025). A tumor composed of atypical neoplastic, often pleomorphic cells that invade other tissues. "Further analysis of NGS identified two novel missense mutations, D326E in BTK (Bruton’s tyrosine kinase) at SH2 domain and D251E in EPHA5 (EPH receptor A5), along with other known cancer- associated mutations." (PMID 39925800, 2025). "The erythropoietin-producing hepatocellular (Eph) receptor A5 (EphA5) has been found to be overexpressed in some malignant tumors and is associated with disease prognosis." (PMID 31956298, 2020). "Similarly, in the Memorial Sloan Kettering Cancer Center (MSKCC) immunotherapy cohort, EPHA5-Mut LUAD cancers also exhibited a significantly higher TMB than EPHA5-WT LUAD cancers, indicating a convincing association between EPHA5 mutations and TMB." (PMID 33288738, 2020). "Stratified correlation analysis across cancer stages revealed stage-specific biological roles of EphA5." (PMID 40806980, 2025). "Given the favorable features of the EphA5 target and the anti-EphA5 mAb, we generated an ADC (termed MBRC-101) to treat EphA5-expressing human cancers." (PMID 40662373, 2025). "We developed and optimized an IHC method to detect the expression of EphA5 in archival tissue sections of various human cancers and corresponding normal tissues." (PMID 40662373, 2025). "The high prevalence of EphA5 in solid tumors and the restricted expression in normal tissues supported the development of a EphA5-targeted, antibody-based therapy to treat human cancers." (PMID 40662373, 2025). "The results emphasize the marked elevation in expression for the majority of EphA genes among cancer patients, except for EphA5, EphA6, and EphA8." (PMID 38952552, 2024). "Ephrin receptor A5 (EPHA5) belongs to Eph/ephrin family and plays an important role in the carcinogenesis of multiple cancers by binding to the ligand." (PMID 36123678, 2022). "While EPHA5 is known to function in cancer in a variety of ways including via the epithelial-to-mesenchymal transition and upregulating cancer stem cell-related markers." (PMID 36376989, 2022). "The cancer genome spectrum showed sarcomatoid HCC group had significant higher mutation rates in CDKN2A, EPHA5, FANCM and MAP3K1." (PMID 34331411, 2021). "In common with other members of the Eph subgroup, EphA5 plays a critical role in the regulation of carcinogenesis and cancer progression." (PMID 25609195, 2015). "The frequency of EphA5 methylation was higher in cancer patients with an elevated Gleason score or T3-T4 staging." (PMID 25609195, 2015). "EphA5 is mostly recognized for its critical role in axonal guidance during embryonic development (17, –, 19); its involvement in cancer is only now becoming evident (20, –, 22)." (PMID 25623065, 2015). "Emerging molecular variants such as Bruton tyrosine kinase (BTK) and Ephrin type-A receptor 5 (EPHA5) promote metabolic reprogramming, drug resistance, and metastasis, and cancer stem cells’ (CSCs) persistence contributes to adaptation to therapy and recurrence." (PMID 41373772, 2025). "Although EphA5 is predominantly studied in the context of neural development, recent evidence suggests that it may also function as an oncogenic driver in certain cancers." (PMID 40806980, 2025). "In several types of human cancers, including NSCLC, mutations in the EPHA5 gene have been found." (PMID 36123678, 2022). "EphA5 is abnormally expressed in numerous malignant tumors and may be involved in cancer’s radiosensitivity." (PMID 34150649, 2021). "However, other previous studies proved that EphA5 was detected to be low-expressed in some other malignant tumors." (PMID 31956298, 2020). "We found that EphA5 overexpression could reverse the cancer-related characteristics in the KYSE150 cells with EphA5 knockdown." (PMID 31956298, 2020).
cancer (continued). "In contrast to these more established roles, EphA5 function in cancer is much less clear." (PMID 27887627, 2016). "According to COSMIC, other interesting cancer related genes are present in these top lists, such as EPHA5, which belongs to the ephrin receptor subfamily of the protein-tyrosine kinase family and PIP4K2B, an enzyme that catalyzes phosphorylation, showing kinase activities." (PMID 27895661, 2016). "In both ACC and SCC, EphA5 was present in the membrane and cytoplasm of cancer cells." (PMID 25623065, 2015). "Second, although we first recognized EphA5 as a cell surface receptor through phage display screenings on human cancer cells, we showed that it is also a cytoplasmic constituent that, like most transcription factors, translocates into the nucleus after irradiation and binds to chromatin." (PMID 25623065, 2015). "Moreover, the significant associations of EphA5 methylation with higher clinicopathologic TNM staging and Gleason score support the important role of EphA5 in cancer progression." (PMID 25609195, 2015). "However, among the patients with late-stage cancer, high DNAJB4 expression was significantly associated with increased levels of caspase-3 (OR: 1.20, p = 0.013), CD31 (OR: 1.06, p = 0.004), and EphA5 (OR: 1.04, p = 0.033), but it was negatively correlated with E-cad expression (OR: 0.93, p = 0.011)." (PMID 40149995, 2025). "Here, we report the design and preclinical evaluation of MBRC-101, a first-in-class antibody-drug conjugate (ADC) targeting EphA5, a receptor tyrosine kinase with an established role in embryonic development but not extensively studied in cancer." (PMID 40662373, 2025). "Expression of EphA5 in cancer has been documented in NSCLC, ovarian, and pancreatic cancers." (PMID 40662373, 2025). "Immunostaining analysis demonstrated that the EphA5 protein was absent or down-regulated in 10 of 13 (76.9%) available carcinoma samples, and 8 of these 10 samples (80.0%) exhibited hypermethylation." (PMID 25609195, 2015). "We designed, generated, and developed MBRC-101, a first-in-class targeted ADC against EphA5, and conducted a comprehensive preclinical program of efficacy and Good Laboratory Practice (GLP) toxicology to support investigational testing in human patients with cancer." (PMID 40662373, 2025). "In contrast, EphA1 and EphA5 demonstrated a distinct negative correlation (Correlation coefficient =−0.36), suggesting intricate co-expression interactions involving numerous EphA genes across diverse cancer types." (PMID 38952552, 2024). "Likewise, we have also detected EphA5 in tumors other than lung (data not shown), raising the possibility that EphA5 might be a molecular target in other human cancers." (PMID 25623065, 2015).
infection (5 papers, 2016 to 2025). The state of being infected such as from the introduction of a foreign agent such as serum, vaccine, antigenic substance or organism. "Another Eph receptor possibly involved in KSHV infection is EphA5 as transduction of an EphA5 (or an EphA4) construct was able to rescue infection in cells that were deficient for EphA2." (PMID 33430066, 2021). "We next assessed the fungal burden in the kidneys of both WT and EphA5-KO mice at 48 hours post infection." (PMID 40489568, 2025). "On the other hand, EphA5, A7 and B4 all suppressed cell fusion, with relative trends comparable to that seen in the infection assay." (PMID 27783670, 2016). "To explore whether EphA5 promoting the migration and invasion was associated with EMT process, we measured the protein levels of EMT markers (E-cadherin, N-cadherin, Snail) in the KYSE150 and KYSE450 cells after siRNA infection." (PMID 31956298, 2020). "As EphA4, EphA5, and EphA7, which are low-affinity receptors for KSHV, are expressed in B cells, these receptors play a crucial role in the infection of B cells by KSHV16,18,19,30." (PMID 33235207, 2020).
peripheral neuropathy (3 papers, 2012 to 2019). A disorder affecting the peripheral nervous system. "The first GWAS on paclitaxel-induced peripheral neuropathy identified three novel genes important in neurite growth during development (EPHA5 and FZD3)." (PMID 30909387, 2019). "Recently, a clinical GWAS with 1040 patients treated with paclitaxel identified 3 SNPs located in the EPHA5, FGD4 and NDRG1 genes that were associated with peripheral neuropathy." (PMID 23006423, 2012). "A previous GWAS from an ongoing phase III clinical trial, CALGB 40101, identified 3 top SNPs located in the EPHA5, FGD4 and NDRG1 genes that were associated with paclitaxel-induced peripheral neuropathy, although none reached genome-wide significance." (PMID 23006423, 2012).
neurodevelopmental disorder (2 papers, 2023). A behavioral and cognitive disorder with onset during the developmental period that involves impaired or aberrant development of intellectual, motor, or social functions. "Within the same subject, we found an additional variant in EPHA5 (EPH receptor A5, MIM 600004), a gene that has not been previously linked to neurodevelopmental disorders." (PMID 38025430, 2023).
psychiatric disorder (1 paper, 2017). A disorder characterized by behavioral and/or psychological abnormalities, often accompanied by physical symptoms. "Ten genes were enrichedwith several KEGG pathways, and ROBO2, CXCL2, EPHA5,EPHA6, ANGPT2, FGF10, GHF genes was found to be enrichedwith pathways influencing psychiatric disorders like Axonguidance, RAP1 Signaling pathways, RAS Signaling pathwaysetc." (PMID 28539732, 2017).